DCAF11 (DDB1 and CUL4 associated factor 11)
Description:
May function as a substrate receptor for CUL4-DDB1 E3 ubiquitin-protein ligase complex.
Synonyms: WDR23; GL014; PRO2389
Tractability: PROTAC: ubiquitination databases record sites on it; its protein half-life has been measured.
Gene: Protein-coding gene on chromosome 14 (24,114,010 to 24,125,614, forward strand). Ensembl gene ENSG00000100897.
Subcellular location (Human Protein Atlas): Nucleoplasm
Pathways (Reactome):
Metabolism of proteins: Neddylation
Gene Ontology:
Molecular function: protein binding
Biological process: proteasome-mediated ubiquitin-dependent protein catabolic process; regulation of cellular response to stress; regulation of mitotic cytokinesis; protein ubiquitination
Cellular component: Cul4-RING E3 ubiquitin ligase complex; nucleoplasm; Cul4A-RING E3 ubiquitin ligase complex; Cul4B-RING E3 ubiquitin ligase complex
Genetic constraint (gnomAD): Loss-of-function variants: 46 observed, 80.93 expected, observed/expected ratio (o/e) 0.57, 90% interval 0.45 to 0.73. The upper end of that interval is the gene's LOEUF score, 0.73, which puts it in group 2 of 6, group 1 being the genes least tolerant of losing a copy. Missense variants: 604 observed, 742.6 expected, observed/expected ratio (o/e) 0.81, 90% interval 0.76 to 0.87. Synonymous variants: 258 observed, 269.77 expected, observed/expected ratio (o/e) 0.96, 90% interval 0.86 to 1.06.
Homologues: Orthologues: chimpanzee DCAF11 (100% identical), dog DCAF11 (96% identical), rat Dcaf11 (94% identical), guinea pig DCAF11 (94% identical), mouse Dcaf11 (94% identical), macaque DCAF11 (93% identical), rabbit DCAF11 (91% identical), pig DCAF11 (87% identical), tropical clawed frog dcaf11 (68% identical), zebrafish dcaf11 (63% identical), Caenorhabditis elegans wdr-23 (33% identical), Drosophila melanogaster CG9945 (32% identical).
Diseases named in the same sentence as DCAF11 in open-access papers:
DCAF11 is named in the same sentence as 14 diseases in open-access papers, as found by Europe PMC text mining. Sharing a sentence is not in itself a finding about the gene and the disease. The quoted sentences say what the papers report.
osteosarcoma (4 papers, 2017 to 2024). A usually aggressive malignant bone-forming mesenchymal neoplasm, predominantly affecting adolescents and young adults. "Our recent study suggests that CUL4B associates with DDB1, RBX1, and DCAF11 to form a unique CRL4BDCAF11 E3 complex in human osteosarcoma cells, and this E3 ligase can specifically target p21Cip1 for degradation, thereby regulating cell cycle progression." (PMID 29377600, 2018). "A study found that in human osteosarcoma cells, CUL4B forms an E3 ligase with RBX1 (RING-box 1), DDB1 (DNA damage binding protein 1), and DCAF11 (DDB1 and CUL4 associated factor 11)." (PMID 39062505, 2024). "Mechanistically, TSC01682 significantly inhibits osteosarcoma cell proliferation and invasion by downregulating DCAF11 and DCAF13 and upregulating CDKN1A (cyclin-dependent kinase inhibitor 1A, also known as p21) and PTEN." (PMID 39062505, 2024). "Recently, we found that CUL4B was overexpressed in osteosarcoma and that the activated CUL4B formed an E3 ligase with DDB1, RBX1, and DCAF11, which further ubiquitinated p21 and caused p21 degradation, resulting in the disruption of cell cycle progression." (PMID 29377600, 2018). "In summary, our results demonstrate that CUL4B forms an E3 ligase with RBX1, DDB1 and DCAF11 to recognize p21 as a substrate in human osteosarcoma cells." (PMID 28446751, 2017). "Our results provide evidence for a potential new DCAF11 pathway in which DCAF11 associates with CUL4B and DDB1 to target p21 for proteolysis in human osteosarcoma cells." (PMID 28446751, 2017). "Here, we demonstrated that CUL4B forms an E3 ligase with RBX1 (RING-box 1), DDB1 (DNA damage binding protein 1), and DCAF11 (DDB1 and CUL4 associated factor 11) in human osteosarcoma cells." (PMID 28446751, 2017). "Activation of the NF-κB axis could enhance CRL4B DCAF11 E3 ligase activity and regulate cell cycle progression in human osteosarcoma cells." (PMID 35515114, 2022). "Knocking down any component of the CRL4BDCAF11 complex, including CUL4B, DDB1 or DCAF11, using short hairpin RNAs (shRNAs) attenuated the ubiquitination level of p21Cip1, inhibited osteosarcoma cell proliferation, led to cell cycle arrest at S phase, and decreased colony formation rate." (PMID 28446751, 2017). "We also observed a significant decrease in CDK2 levels after down-regulation of CUL4B, DDB1 or DCAF11 in osteosarcoma cells, which raised the question of whether DCAF11 is responsible for the degradation of CDK2." (PMID 28446751, 2017). "To confirm this hypothesis, we examined DCAF4 and DCAF11 protein levels in different osteosarcoma cell lines." (PMID 28446751, 2017). "As expected, osteosarcoma cells expressing lower levels of CUL4B, DDB1 or DCAF11 exhibited dramatically higher percentages of cells in S phase." (PMID 28446751, 2017). "Fortunately, we found that DCAF11 had a similar expression pattern to CUL4B and was upregulated in different osteosarcoma cells." (PMID 28446751, 2017). "DCAF11, instead of DCAF4, was significantly induced in U2OS, MG63, Saos-2 and HOS osteosarcoma cell lines compared with hFOB1.19 cells." (PMID 28446751, 2017). "Thus, CDK2 might be only a CUL4B-associated protein, and its down-regulation in osteosarcoma cells expressing lower CUL4B, DDB1 or DCAF11 might not be regulated by DCAF11 but might rather be regulated by p21 induction, as p21 is an inhibitor of CDK2." (PMID 28446751, 2017). "The CUL4B-Flag immunocomplex from hFOB1.19, U2OS or Saos-2 cells pulled down DCAF4 and DCAF11, but not DCAF1, 8 and 15, indicating that these two DCAFs form complexes with CUL4 and DDB1 in osteosarcoma cells." (PMID 28446751, 2017). "By examining the protein levels of several DCAFs in osteosarcoma cells, we found that DCAF11 was specifically upregulated, whereas other DCAFs, such as DCAF1, 4, 8, and 15, were not, and we then determined the interactions between DCAF11 and DDB1." (PMID 28446751, 2017).
breast carcinoma (1 paper, 2020). "A similar CUL4 IP/MS study performed on a transfected human BT474 breast cancer line recovered two DCAF receptors: DCAF11 and human immunodeficiency virus type 1 Viral Protein R (Vpr)-binding protein (VPRBP), of the approximately 60 DCAFs encoded in the human genome." (PMID 32235678, 2020).
influenza infection (1 paper, 2024). "A global loss of interacting protein partners during influenza infection is observed for both DDB1 and DCAF11, which interact respectively with 69 and 73 proteins only in non-infected cells, and with 19 and 33 exclusively in infected cells." (PMID 39383947, 2024).
tumor (4 papers, 2016 to 2025). "Antiproliferative activity of DCAF11 PROTACs against different tumor entities." (PMID 39973224, 2025).
infection (3 papers, 2018 to 2024). The state of being infected such as from the introduction of a foreign agent such as serum, vaccine, antigenic substance or organism. "Additionally, DCAF11 engaged associations with transcription and chromatin factors, which were lost following infection." (PMID 39383947, 2024). "GO-term enrichment analysis pointed to the loss of factors regulating host translation, metabolism of RNA, and influenza A infection upon infection, while the DCAF11’s targeting upon infection affected cellular responses to stress and stimuli." (PMID 39383947, 2024). "Different binding profiles emerged, with the number of associated partners decreasing upon infection for DDB1 and DCAF11, while DCAF12L1 gained interactors." (PMID 39383947, 2024). "Infection-induced alterations in the binding profiles of DCAF11 and DCAF12L1 targeted common cellular processes, including translation, RNA metabolism, and transcription, all intricately regulated through ubiquitination." (PMID 39383947, 2024). "A significant rewiring of the CRL4s interaction partners was observed, particularly for DDB1 for which only 26% of the 119 interactors remained constant upon infection, whereas 49% and 65% remained unchanged for DCAF11 and DCAF12L1, respectively." (PMID 39383947, 2024). "To assess the functional relevance of our datasets, we first conducted literature mining to determine the role of 41 host proteins that differentially interacted with either DCAF11 or DCAF12L1 upon infection." (PMID 39383947, 2024). "Additionally, positive interactors of DCAF11 that were lost upon infection encompass splicing factors THRAP3 and SRSF5, the microtubule-associated protein MAP4, mitochondrial ribosomal protein MRPL12, and the TUFM mitochondrial translation elongation factor." (PMID 39383947, 2024). "Our results revealed substantial modulations in the interaction networks of the three factors, DDB1, DCAF11, and DCAF12L1, characterized by a comprehensive reduction in DDB1 and DCAF11 interactions, while DCAF12L1 interactors increased upon infection." (PMID 39383947, 2024).
DCAF11 also shares sentences with these, for which no sentence is quoted: cancer (2 papers); diabetes (1); Hepatic steatosis (1); Hyperglycemia (1); kidney cancer (1); lung carcinoma (1); metabolic disease (1); non-small cell lung carcinoma (1); stomach cancer (1).